IGHV4-61 (immunoglobulin heavy variable 4-61)
Description:
V region of the variable domain of immunoglobulin heavy chains that participates in the antigen recognition. Immunoglobulins, also known as antibodies, are membrane-bound or secreted glycoproteins produced by B lymphocytes. In the recognition phase of humoral immunity, the membrane-bound immunoglobulins serve as receptors which, upon binding of a specific antigen, trigger the clonal expansion and differentiation of B lymphocytes into immunoglobulins-secreting plasma cells. Secreted immunoglobulins mediate the effector phase of humoral immunity, which results in the elimination of bound antigens. The antigen binding site is formed by the variable domain of one heavy chain, together with that of its associated light chain. Thus, each immunoglobulin has two antigen binding sites with remarkable affinity for a particular antigen. The variable domains are assembled by a process called V-(D)-J rearrangement and can then be subjected to somatic hypermutations which, after exposure to antigen and selection, allow affinity maturation for a particular antigen.
Synonyms: IGHV461; VH
Gene: Immunoglobulin variable (V) gene on chromosome 14 (106,639,119 to 106,639,657, reverse strand). Ensembl gene ENSG00000211970.
Subcellular location: Secreted; Cell membrane
Gene Ontology:
Molecular function: antigen binding
Biological process: immunoglobulin mediated immune response
Cellular component: extracellular region; plasma membrane
Genetic constraint (gnomAD): Missense variants: 12 observed, 5.19 expected, observed/expected ratio (o/e) 2.31. Synonymous variants: 6 observed, 2.75 expected, observed/expected ratio (o/e) 2.18.
Homologues: Paralogues in human: IGHV4-59 (97% identical), IGHV4-39 (95% identical), IGHV4-31 (92% identical), IGHV4-4 (92% identical), IGHV4-28 (91% identical), IGHV4OR15-8 (91% identical), IGHV4-34 (89% identical), IGHV6-1 (64% identical), IGHV2-26 (57% identical), IGHV3-11 (56% identical), IGHV2-5 (55% identical), IGHV2-70 (54% identical), and 65 more.